SNX29 (sorting nexin 29)
Synonyms: RUNDC2A; FLJ12363; A-388D4.1
Tractability: PROTAC: ubiquitination databases record sites on it; its protein half-life has been measured.
Gene: Protein-coding gene on chromosome 16 (11,976,734 to 12,574,287, forward strand). Ensembl gene ENSG00000048471.
Subcellular location (Human Protein Atlas): Golgi apparatus; Cytosol; Nucleoli
Gene Ontology:
Molecular function: phosphatidylinositol binding
Genetic constraint (gnomAD): Loss-of-function variants: 76 observed, 97.1 expected, observed/expected ratio (o/e) 0.78, 90% interval 0.65 to 0.95. The synonymous counts are far from expectation, so gnomAD's model fits this gene poorly and the ratio says little. Missense variants: 1,244 observed, 1,048.4 expected, observed/expected ratio (o/e) 1.19, 90% interval 1.13 to 1.24. Synonymous variants: 567 observed, 411.6 expected, observed/expected ratio (o/e) 1.38, 90% interval 1.28 to 1.48.
Homologues: Orthologues: macaque SNX29 (99% identical), chimpanzee SNX29 (97% identical), dog SNX29 (93% identical), pig SNX29 (91% identical), guinea pig SNX29 (90% identical), rabbit SNX29 (90% identical), mouse Snx29 (87% identical), rat Snx29 (87% identical), tropical clawed frog snx29 (72% identical), zebrafish snx29 (62% identical), Drosophila melanogaster CG31064 (12% identical), Caenorhabditis elegans lst-2 (7% identical), and 1 more. Paralogues in human: PLEKHM2 (15% identical), RUFY2 (14% identical), RUFY1 (14% identical), RUFY3 (13% identical), ZFYVE26 (12% identical), RUNDC3B (12% identical), ZFYVE28 (11% identical), RUNDC3A (11% identical), ZFYVE1 (9% identical), ZFYVE16 (6% identical), ZFYVE19 (6% identical), PLEKHF2 (5% identical), and 1 more.
Diseases named in the same sentence as SNX29 in open-access papers:
SNX29 is named in the same sentence as 17 diseases in open-access papers, as found by Europe PMC text mining. Sharing a sentence is not in itself a finding about the gene and the disease. The quoted sentences say what the papers report.
bipolar disorder (2 papers, 2022 to 2025). A disorder of the brain that causes unusual shifts in mood, energy, activity levels and the ability to carry out day-to-day tasks. "SNX29, involved in nervous system development, is a risk gene for several neurological disorders, including SZ and bipolar disorder, but its relation to neural oscillations has not yet been studied." (PMID 40806641, 2025).
gastric cancer (2 papers, 2022 to 2023). A primary or metastatic malignant neoplasm involving the stomach. "SNX29 seemed to be the next research hotspot of immune regulation in gastric cancer, for its positive correlation with all the four TIICs types." (PMID 35715463, 2022).
diffuse large B-cell lymphoma (1 paper, 2023). "Kaplan–Meier analysis showed that patients with higher SNX29 levels had shorter OS in BLCA (p = 0.0052), lymphoid neoplasm diffuse large B-cell lymphoma (DLBC) (p = 0.0208), lung squamous cell carcinoma (LUSC) (p = 0.017), skin cutaneous melanoma (SKCM) (p = 0.0422), and STAD (p = 0.0467)." (PMID 36829159, 2023).
ovarian serous cystadenocarcinoma (1 paper, 2023). A malignant serous cystic epithelial neoplasm arising from the ovary. "In the OS analysis, Cox regression analysis revealed that high SNX29 expression was a protective factor for BLCA (p = 0.007), STAD (p = 0.014), ovarian serous cystadenocarcinoma (OV) (p = 0.009), and LIHC (p = 0.031)." (PMID 36829159, 2023).
testicular germ cell tumor (1 paper, 2023). A germ cell tumor arising from the testis. "SNX29 expression was associated with the clinical stage of several cancers, including BLCA (p = 0.013), KIRC (p = 0.00034), LUAD (p = 0.0044), testicular germ cell tumor (TGCT) (p = 0.031), and THCA (p = 0.011)." (PMID 36829159, 2023).
tumor (3 papers, 2021 to 2023). "Taken together, the results of this study provide clues to the association between SNX29 and tumor immunotherapy." (PMID 36829159, 2023). "In most tumors, SNX29 expression was associated with a decrease in tumor purity; this was the case for LAML, LUAD, READ and STAD." (PMID 36829159, 2023). "The results showed that the SNX29 gene was significantly associated with the sensitivity of various tumor cell lines to nine antitumor drugs, including vorinostat, 7-hydroxystaurosporine, idelalisib, cabozantinib, calusterone, vismodegib, perifosine, rapamycin and panobinostat." (PMID 36829159, 2023). "Finally, the expression of SNX29 was significantly associated with the sensitivity of various tumor cell lines to 8 antitumor drugs." (PMID 36829159, 2023). "In addition, we found associations between the SNX29 gene and tumor mutation burden, microsatellite instability, immunoinhibition-related genes and autophagy-related genes." (PMID 36829159, 2023). "To assess the SNX29 protein expression profile across cancers, we assessed SNX29 expression in various tumor and normal tissues using HPA." (PMID 36829159, 2023). "Our current study revealed that the expression of SNX29 was significantly increased in tumor tissues and was correlated with the prognosis and clinical staging across cancers." (PMID 36829159, 2023). "The expression of SNX29 was found to be significantly upregulated in most tumor tissues compared to normal tissues." (PMID 36829159, 2023). "Among the 33 cancers investigated, SNX29 gene expression was significantly different between normal and tumor samples in 14 cancers." (PMID 36829159, 2023). "In our current research, SNX29 expression showed a robust negative association with tumor purity based on ESTIMATE analysis in most cancers, such as LAML, LUAD, READ and STAD." (PMID 36829159, 2023). "Interestingly, SNX29 expression was decreased in tumor tissues in BRCA, COAD, LUSC, READ, SKCM and THCA." (PMID 36829159, 2023). "The significance of such enrichment reaches p < 10−58 for CACNA1C and SNX29 from the Network of Cancer Genes, and p < 10−61 for WWOX and CSMD1 from the Tumor Suppressor Gene Database." (PMID 33741065, 2021). "Following the co-expression and network analyses, this signature was found to be enriched for genes involved in the regulation of the stroma component of the tumor (TDO2, STEAP1) as well as Treg cells (SLC16A1, PRKAB1) and myeloid cell (APOBEC3A, MERTK, SNX29) subsets." (PMID 36216827, 2022).
cancer (2 papers, 2021 to 2023). A tumor composed of atypical neoplastic, often pleomorphic cells that invade other tissues. "We showed that SNX29 expression was associated with most genes in most cancers, such as ATG2B, EPG, AMBRA1, and BECN1, in most cancers." (PMID 36829159, 2023). "We explored five cancers in which the SNX29 gene was strongly associated with patient survival." (PMID 36829159, 2023). "High SNX29 expression was negatively correlated with ICB response in some cancers, including KIRC and LGG." (PMID 36829159, 2023). "This pan-cancer study of SNX29 gene expression, prognostic assessment, immune infiltration and potential drug therapeutic targets in 33 tumors was conducted in a comprehensive and systematic manner." (PMID 36829159, 2023). "To explore the intrinsic mechanism of SNX29 expression in immunoinhibition-related genes, we analyzed the correlation between SNX29 expression and immunoinhibition-related genes in 33 cancer types." (PMID 36829159, 2023). "Through KEGG analysis, our current study revealed that the focal adhesion pathway is the most common signaling pathway in which SNX29 is involved across cancers." (PMID 36829159, 2023). "First, analysis based on TCGA and GTEx data showed that SNX29 was expressed at relatively higher levels in 14 different cancers compared to normal controls." (PMID 36829159, 2023). "The expression of SNX29 in 33 human cancers was analyzed using the TCGA and GTEx datasets." (PMID 36829159, 2023). "The expression of SNX29 in 33 human cancers was analyzed using the TCGA." (PMID 36829159, 2023). "SNX29 seemed to be the next research hotspot in various cancers." (PMID 36829159, 2023). "This study provides novel insights into the potential pan-cancer targets of SNX29." (PMID 36829159, 2023). "Thus, SNX29 could potentially serve as a predictor of the efficacy of immunotherapy in these cancer types." (PMID 36829159, 2023). "Our study showed significant positive correlations between SNX29 expression and stromal, immune and ESTIMATE scores in most cancers, such as BLCA, BRCA, COAD and LAML." (PMID 36829159, 2023). "The relationships between the SNX29 gene and clinical prognosis as well as pan-cancer cell infiltration and drug sensitivity have not been fully elucidated." (PMID 36829159, 2023).
SNX29 also shares sentences with these, for which no sentence is quoted: schizophrenia (2 papers); Anorexia (1); Hypertension (1); lung squamous cell carcinoma (1); lymphoid neoplasm (1); major depressive disorder (1); neurological disorders (1); Pan (1); Parkinson disease (1); skin cutaneous melanoma (1).